U3 (Small nucleolar RNA U3 )
Synonyms: LOC124901508
Gene: Small nucleolar RNA gene on chromosome 6 (71,126,893 to 71,127,105, reverse strand). Ensembl gene ENSG00000221345.
Gene Ontology:
Biological process: RNA processing
Cellular component: nucleolus
Homologues: Orthologues: chimpanzee U3 (97% identical), macaque U3 (92% identical), dog U3 (74% identical). Paralogues in human: SNORD3P1 (80% identical), U3 (80% identical), U3 (79% identical), U3 (78% identical), SNORD3D (77% identical), SNORD3E (77% identical), U3 (77% identical), SNORD3G (77% identical), U3 (76% identical), U3 (75% identical), U3 (74% identical), SNORD3H (73% identical), and 14 more.